IGLON5 (IgLON family member 5)
Diseases named in the same sentence as IGLON5 in open-access papers (continued):
Sharing a sentence is not in itself a finding about the gene and the disease.
autoimmune disorder of the central nervous system (2 papers, 2024 to 2026). "Anti-IgLON5 disease is a recently defined autoimmune disorder of the central nervous system associated with autoantibodies against IgLON5." (PMID 41755996, 2026). "Anti-IgLON5 antibody-related encephalitis, also known as anti-IgLON5 syndrome, is a rare autoimmune disorder of the central nervous system with sleep disturbances as its core symptom." (PMID 38765268, 2024). "Anti-IgLON5 antibody-related encephalitis is a rare autoimmune disorder of the central nervous system, predominantly occurring in middle-aged elderly individuals, with paediatric cases being exceptionally rare." (PMID 38765268, 2024).
gaze palsy (2 papers, 2022 to 2025). "Patients with gaze palsy and postural instability diagnosed with PSP can develop these symptoms as a result of anti-IgLON5." (PMID 41445985, 2025).
psychosis (2 papers, 2023 to 2024). "In a series of 53 patients with anti-IgLON5 disease, only nine (17%) developed psychosis or hallucinations." (PMID 38370417, 2024). "Herein, we illustrate an unusual case of a patient primarily exhibiting RPD, overlapping sleep dysfunction, psychosis and abnormal movement, which was finally defined as anti-IgLON5 disease, a novel and rare autoimmune encephalopathy." (PMID 37090977, 2023).
rapid eye movement sleep behavior disorder (2 papers, 2018 to 2022). "Characteristic findings for anti-IgLON5 disease in VPSG examination are abnormal NREM sleep initiation, rapid eye movement sleep behavior disorder (RBD), motor activation and breathing problems such as stridor and apnea." (PMID 35300333, 2022).
autism spectrum disorder (1 paper, 2016). A spectrum of developmental disorders that includes autism, and Asperger syndrome. "Although the physiological role of IgLON5 is unknown, other members of the IgLON family are involved in neuronal pathfinding and synaptic formation during brain development and have been implicated in the pathogenesis of autism spectrum disorders and epigenetics of tumor progression." (PMID 27586161, 2016).
cardiac amyloidosis (1 paper, 2025). Cardiac amyloidosis is a condition whereby cardiac tissue is infiltrated by amyloid fibrils. "Other cases with anti-IgLON5 disease and sensorimotor polyneuropathy were described, though the presence or absence of cardiac amyloidosis in these cases is unclear." (PMID 41008281, 2025).
cardiac arrest (1 paper, 2025). Cessation of breathing and/or cardiac function. "Cardiac arrests and other cardiac complications are repeatedly reported in patients with anti-IgLON5 disease, and Gaig and colleagues have suggested a link between cardiac complications and sudden death in these patients." (PMID 41008281, 2025).
cervical dystonia (1 paper, 2020). "Jaw and cervical dystonia might rarely be seen in patients with IgLON5-antibodies, but with further classical signs of IgLON5-disease like gait instability, bulbar symptoms and sleep abnormalities." (PMID 33324912, 2020).
Dyskinesia (1 paper, 2023). A movement disorder which consists of effects including diminished voluntary movements and the presence of involuntary movements. "Low titer IgLON5 antibodies were present in serum from one dog from the epilepsy/dyskinesia group and in one dog from the control group." (PMID 37232512, 2023). "This antibody appeared of uncertain relevance, because cell‐based assays showed IgLON5 antibodies in one dog from the epilepsy/dyskinesia group and one dog from the control group." (PMID 37232512, 2023). "Cell‐based assays which express human antigens provided negative results for each tested neural AB in all dogs except low serum AB titers of IgLON5 antibodies (1:40) in one dog with unclassified episodes from the epilepsy/dyskinesia group, but also in one dog from the control group." (PMID 37232512, 2023).
meningeal carcinomatosis (1 paper, 2025). "After exclusion of patients without clinical data (n = 3) or with alternative diagnoses (meningeal carcinomatosis, n = 2), 52 patients with anti-IgLON5 disease were included in the study." (PMID 40106089, 2025).
multisystem atrophy (1 paper, 2023). "Patients with LGI1, IgLON5, DPPX and GABABR antibodies have been misdiagnosed with Parkinson’s disease (PD), progressive supranuclear palsy (PSP), cortico-basal syndrome (CBS) or multisystem atrophy (MSA)." (PMID 36979644, 2023).
myasthenia (1 paper, 2017). "Recent studies have found strong associations of certain HLA alleles in diverse tissue-specific IgG4-mediated diseases, such as LGI1 encephalitis (DRB1*07:01–DQB1*02:02 haplotype), anti-MusK myasthenia (DR14-DQ5 haplotype), or anti-IgLON5 disease (DRB1*10:01-DQB1*05:01)." (PMID 29145880, 2017).
myocardial infarction (1 paper, 2024). Gross necrosis of the myocardium, as a result of interruption of the blood supply to the area, as in coronary thrombosis. "Verification using RT-qPCR showed that myocardial infarction caused decreased miR-10a-5p expression and increased IGLON5 expression." (PMID 39057097, 2024). "For IgLON5, information is only available about microRNA involved in myocardial infarction." (PMID 39057097, 2024).
Nystagmus (1 paper, 2021). Rhythmic, involuntary oscillations of one or both eyes related to abnormality in fixation, conjugate gaze, or vestibular mechanisms. "IV) We found spontaneous nystagmus and gaze evoked nystagmus in all our patients suffering from anti-IgLON5 disease but only in 50% of our patients with PSP." (PMID 34659261, 2021). "Patients with anti-IgLON5 disease presented with horizontal spontaneous nystagmus (2/4), upbeat nystagmus (1/4) and bidirectional gaze evoked nystagmus (1/4)." (PMID 34659261, 2021).
Perry syndrome (1 paper, 2024). Perry syndrome is a rare inherited neurodegenerative disorder characterized by rapidly progressive early-onset parkinsonism, central hypoventilation, weight loss, insomnia and depression. "However, we are not aware of any studies analyzing mutations in the DCTN1 gene in anti-IgLON5 disease cases or, conversely, the presence of anti-IgLON5 antibodies in Perry syndrome." (PMID 39400557, 2024). "While clinical features may overlap with those of anti-IgLON5 disease, the neurodegenerative features with prominent neuronal loss, axonal spheroids and pigment that are characteristic findings in Perry syndrome were absent in all cases with anti-IgLON5 disease so far." (PMID 39400557, 2024).
proteinopathies (1 paper, 2024). "We had the opportunity to re-evaluate previously reported cases and assessed new patients with anti-IgLON5 disease who underwent a neuropathological examination, with the aim to characterize the spectrum of underlying pathologies/proteinopathies." (PMID 39400557, 2024).
rectal cancer (1 paper, 2023). A primary or metastatic malignant neoplasm that affects the rectum. "We herein described a patient with anti-IgLON5 disease complicated with rectal cancer who achieved relief of clinical symptoms after the plasma exchange and immunosuppression treatment." (PMID 36597054, 2023). "We described an unusual entity of anti-IgLON5 disease complicated with rectal cancer." (PMID 36597054, 2023). "Anti-IgLON5 disease complicated with rectal cancer is very rare." (PMID 36597054, 2023). "Several studies have described its clinical characteristics, however, the simultaneous occurrence of anti-IgLON5 disease and rectal cancer has not been reported." (PMID 36597054, 2023).
renal carcinoma (1 paper, 2022). A carcinoma arising from the epithelium of the renal parenchyma or the renal pelvis. "Expression of the IgLON5 gene correlates with unfavorable renal cancer survival expectancy, but it is still thought that paraneoplastic activity of IgLON5 expression is rare." (PMID 35300333, 2022).
renal neoplasia (1 paper, 2022). "Furthermore, recent literature indicates a correlation between anti-IgLON5 disease and the occurrence of schizophrenia and renal neoplasia." (PMID 35300333, 2022).
Respiratory insufficiency (1 paper, 2016). "The clinical history of the three patients in whom IgLON5 antibodies were not tested was dominated by bulbar dysfunction and repetitive episodes of respiratory insufficiency that required tracheostomy or multiple admissions to ICU." (PMID 27358064, 2016).
synucleinopathies (1 paper, 2022). "Finally, transcripts known to be involved in Tau- and synucleinopathies include IGLON5, CAV1, GFRA2, SYNGR3, and SLC6A3, with the latter being particularly interesting as its genetic variants lead to Parkinsonism-dystonia infantile (PKDYS) syndrome." (PMID 35883433, 2022).
Ventriculomegaly (1 paper, 2024). An increase in size of the ventricular system of the brain. "Although ventriculomegaly was observed in a patient with anti-IgLON5 disease, the brain MRI of most (>90%) patients showed a similar degree of atrophy as that of age-matched controls or only a mild atrophy of the brainstem." (PMID 38370417, 2024).
neurological disorder (17 papers, 2016 to 2025). "Many clinical studies have shown that autopsies of patients with anti-IgLON5 antibody-associated neurological disorders reveal the deposition of phosphorylated Tau protein in certain regions of the midbrain, brainstem, and cerebellum." (PMID 37760924, 2023). "Although we appreciated some parallels in clinical manifestations to IgLON5 disease in humans the finding of a low positive titer in a control dog argues against a significant association with neurologic disease in dogs." (PMID 37232512, 2023). "Anti-IgLON5 disease is a rare neurological disorder associated with autoantibodies against the neuronal cell adhesion protein, IgLON5." (PMID 35690819, 2022). "Anti-IgLON5 disease is a progressive neurological disorder associated with autoantibodies against a neuronal cell adhesion molecule, IgLON5." (PMID 33917676, 2021). "Anti-IgLON5 antibodies are associated with a novel category of neurological disease, cell surface antibody-associated neurodegeneration, at the border between autoimmune and neurodegenerative disease." (PMID 28878733, 2017). "Anti-IgLON5 disease is a recently characterized neurological disorder associated with antibodies targeting IgLON5 (IgLON5-Abs), a neuronal surface protein of unknown function." (PMID 40106089, 2025). "Anti-IgLON5 disease is a neurological disorder that is associated with autoantibodies against IgLON5, a cell adhesion molecule belonging to the IgLON (immunoglobulin LAMP, OBCAM and neurotrimin) subgroup of the immunoglobulin superfamily and strongly expressed in neurons." (PMID 37646790, 2023). "Background/Objectives: Anti-IgLON5 disease is a neurological disorder characterized by the presence of autoantibodies directed against the neuronal cell adhesion protein IgLON5." (PMID 41008281, 2025). "Anti-IgLON5 disease is a neurological disorder characterized by autoantibodies against IgLON5 and pathological evidence of neurodegeneration." (PMID 38370417, 2024). "Anti-IgLON5 disease is a rare neurological disorder characterized by autoantibodies against IgLON5, and pathological evidence of neurodegeneration." (PMID 37033996, 2023). "Anti-IgLON5 disease is a novel neurological disorder, thought to be autoantibody mediated, but with a distinct neurodegenerative pattern on postmortem tissue." (PMID 33917676, 2021). "Anti-IgLON5 disease is a neurological disorder characterized by the presence in serum, and >90% of cases are in cerebrospinal fluid (CSF), with IgG antibodies targeting IgLON5, a neuronal cell adhesion molecule of unknown function." (PMID 38370417, 2024). "Antibodies against IgLON5, a neuronal adhesion protein of unknown function, are markers of a novel neurological disorder termed anti-IgLON5 syndrome." (PMID 27586161, 2016). "Still, patients with anti-IgLON5 disease have no family history of a neurological disorder and are considered to suffer from a sporadic disease form." (PMID 39400557, 2024). "Unlike other neurological disorders targeting neuronal cell surface antigens, the clinical progression of anti-IgLON5 disease is usually chronic with limited response to immunotherapy." (PMID 37033996, 2023).
movement disorder (12 papers, 2018 to 2026). Neurological conditions resulting in abnormal voluntary or involuntary movement, which may impact the speed, fluency, quality and ease of movement. "The movement disorders appear to be linked to the impaired dopaminergic pathway, and the increased p-Tau showed neurodegenerative changes induced by the anti-IgLON5 antibody." (PMID 37760924, 2023). "The objective of this study is to explore the underlying mechanisms of movement disorders caused by anti-IgLON5 antibodies for the first time." (PMID 37760924, 2023). "Our previous studies have explored the mechanisms of anti-IgLON5 antibody-mediated cognitive impairments, but there is still a lack of understanding regarding the underlying mechanisms of movement disorders in this disease." (PMID 37760924, 2023). "In this study, we utilized passive immunization by infusing antibodies into the SNc of mice to establish a stable mouse model of movement disorders associated with anti-IgLON5 disease." (PMID 37760924, 2023). "However, there is still a lack of in-depth exploration into the mechanisms underlying anti-IgLON5 antibody-mediated movement disorders." (PMID 37760924, 2023). "Anti-IgLON5 antibodies were detected in patients suffering from sleep problems, movement disorders, bulbar symptoms and cognitive decline." (PMID 40930030, 2025). "This study primarily observed the characteristics and duration of anti-IgLON5 antibody-mediated movement disorder, partially explaining their relationship with neurodegeneration." (PMID 37760924, 2023). "This study aims to establish the first mouse model of anti-IgLON5 antibody-mediated movement disorders and conduct longitudinal observations." (PMID 37760924, 2023). "Further experimental studies on the effects of anti-IgLON5 antibodies on sleep and movement disorders are needed." (PMID 35690819, 2022). "In this French cohort, by the time of diagnosis, all patients had a multidomain clinical presentation, a similar figure than in the ICS development cohorts, with a predominance of bulbar, sleep, and movement disorders, which is consistent with the classical clinical profile of anti-IgLON5 disease." (PMID 40106089, 2025). "As sleep‐related disorders are often not the leading reason for consultation and only revealed by PSG examination, we suggest that screening for antibodies against IgLON5 should be considered in patients presenting with unexplained movement disorders, including isolated hemichorea." (PMID 36698996, 2022).
neurodegenerative disease (8 papers, 2017 to 2026). A disorder of the central nervous system characterized by gradual and progressive loss of neural tissue and neurologic function. "Similar to neurodegenerative diseases, anti-IgLON5 disease often exhibits a chronic course, which is different from anti-NMDA receptor encephalitis and typically presents rapidly within days or weeks." (PMID 37760924, 2023). "An exception is IgLON5 disease, possibly because it presents an intriguing link between more common neurodegenerative diseases and AE." (PMID 38201219, 2023). "The clinical phenotype of anti-IgLON5 disease mainly comprises features of a neurodegenerative disease." (PMID 34659261, 2021). "Anti-IgLON5 disease forms an interface between neuroinflammation and neurodegeneration and includes clinical phenotypes that are often similar to those of neurodegenerative diseases." (PMID 34659261, 2021). "An early diagnosis of patients with anti-IgLON5 disease and differentiation from neurodegenerative diseases is necessary and may have therapeutic implications." (PMID 34659261, 2021). "We find that patient-derived α-IgLON5 AABs cluster IgLON5 proteins with other cell surface proteins, leading to neuronal hyperactivity that triggers pathological Tau missorting and phosphorylation, typically observed early in Tau-related neurodegenerative diseases." (PMID 42127169, 2026). "The novelty of our work is that ocular motor parameters were examined for the first time in anti-IgLON5 disease using VOG and compared with data from neurodegenerative diseases and CON." (PMID 34659261, 2021).
tumor (5 papers, 2016 to 2025). "Tumor screening should be considered in patients with anti-IgLON5 disease to investigate the association between tumor and this disease." (PMID 36597054, 2023). "Staining for CADM3, IGLON5, and TGFB1 was low in tumor tissue; staining for LEP and ABI3BP was medium in tumor tissue; staining for CD1B was high in tumor tissue." (PMID 34497681, 2021).
infection (2 papers, 2024 to 2025). The state of being infected such as from the introduction of a foreign agent such as serum, vaccine, antigenic substance or organism. "Antibodies to NMDAR, GAD, and MOG have been linked to both infection and vaccination, while CASPR-2 and IgLON5 are only associated with infection." (PMID 41311428, 2025). "The presence of positive IgLON5 antibodies in CSF is indicative of an autoimmune response triggered post-infection." (PMID 39224609, 2024).
peripheral neuropathy (2 papers, 2020 to 2022). A disorder affecting the peripheral nervous system. "A recently published case report revealed another possible feature responsible for gait abnormality in anti-IgLON5 disease – bilateral vestibulopathy, which appears to be another sign of peripheral neuropathy in this condition." (PMID 35300333, 2022).
neurodevelopmental disorder (1 paper, 2023). A behavioral and cognitive disorder with onset during the developmental period that involves impaired or aberrant development of intellectual, motor, or social functions. "In addition, the discovery of the autoimmune response associated with anti-IgLON5 disease hints to a possible involvement of autoimmune responses as a contributing mechanism of action in other neurodegenerative and neurodevelopmental disorders associated with this family." (PMID 37895235, 2023).
overlap syndrome (1 paper, 2024). "Both domestic and international reports have documented cases of anti-IgLON5 antibody overlap syndrome with LGI1 antibodies." (PMID 38765268, 2024).
IGLON5 also shares sentences with these, for which no sentence is quoted: insomnia (5 papers); dementia (4); Sleep disturbance (4); Stridor (4); dysautonomia (3); amyotrophic lateral sclerosis (2); corticobasal degeneration (2); encephalomyelitis (2); Epileptic Seizures (2); fragile X-associated tremor/ataxia syndrome (2); frontotemporal lobar degeneration (2); memory impairment (2); Mycoplasma pneumonia (2); Myoclonus (2); narcolepsy (2); Postural instability (2); respiratory failure (2); Sjögren syndrome (2); sporadic Creutzfeldt-Jakob disease (2); viral infection (2); vitiligo (2); argyrophilic grain disease (1); aspiration pneumonia (1); asthma (1); Atrophy (1); autonomic dysfunction (1); Behcet disease (1); Brain atrophy (1); cancer (1); celiac disease (1).
A further 52 diseases each share a sentence with IGLON5 in 1 paper.